CYP7B1 (cytochrome P450 family 7 subfamily B member 1)
Description:
A cytochrome P450 monooxygenase involved in the metabolism of endogenous oxysterols and steroid hormones, including neurosteroids. Mechanistically, uses molecular oxygen inserting one oxygen atom into a substrate, and reducing the second into a water molecule, with two electrons provided by NADPH via cytochrome P450 reductase (CPR; NADPH-ferrihemoprotein reductase). Catalyzes the hydroxylation of carbon hydrogen bonds of steroids with a preference for 7-alpha position. Usually metabolizes steroids carrying a hydroxy group at position 3, functioning as a 3-hydroxy steroid 7-alpha hydroxylase. Hydroxylates oxysterols, including 25-hydroxycholesterol and (25R)-cholest-5-ene-3beta,26-diol toward 7-alpha hydroxy derivatives, which may be transported to the liver and converted to bile acids. Via its product 7-alpha,25-dihydroxycholesterol, a ligand for the chemotactic G protein-coupled receptor GPR183/EBI2, regulates B cell migration in germinal centers of lymphoid organs, thus guiding efficient maturation of plasma B cells and overall antigen-specific humoral immune response (By similarity). 7-alpha hydroxylates neurosteroids, including 3beta-hydroxyandrost-5-en-17-one (dehydroepiandrosterone) and pregnenolone, both involved in hippocampus-associated memory and learning. Metabolizes androstanoids toward 6- or 7-alpha hydroxy derivatives.
Synonyms: CBAS3; CP7B; SPG5A
Tractability: Antibody: UniProt predicts a signal peptide or a membrane-spanning region. PROTAC: ubiquitination databases record sites on it; its protein half-life has been measured.
Target class: Enzyme; Oxidoreductase
Gene: Protein-coding gene on chromosome 8 (64,587,763 to 64,799,145, reverse strand). Ensembl gene ENSG00000172817.
Subcellular location: Endoplasmic reticulum membrane; Microsome membrane
Pathways (Reactome):
Metabolism: Endogenous sterols; Synthesis of bile acids and bile salts; Synthesis of bile acids and bile salts via 27-hydroxycholesterol; Synthesis of bile acids and bile salts via 7alpha-hydroxycholesterol
Disease: Defective CYP7B1 causes SPG5A and CBAS3
Gene Ontology:
Molecular function: 25-hydroxycholesterol 7-alpha-hydroxylase activity; protein binding; 24S-hydroxycholesterol 7-alpha-hydroxylase activity; oxysterol 7-alpha-hydroxylase activity; steroid hydroxylase activity; heme binding; iron ion binding; monooxygenase activity; oxidoreductase activity, acting on paired donors, with incorporation or reduction of molecular oxygen
Biological process: B cell chemotaxis; bile acid biosynthetic process; cholesterol homeostasis; sterol metabolic process; steroid metabolic process
Cellular component: endoplasmic reticulum membrane
Genetic constraint (gnomAD): Loss-of-function variants: 27 observed, 41.9 expected, observed/expected ratio (o/e) 0.64, 90% interval 0.47 to 0.89. The upper end of that interval is the gene's LOEUF score, 0.89, which puts it in group 3 of 6, group 1 being the genes least tolerant of losing a copy. Missense variants: 641 observed, 604.4 expected, observed/expected ratio (o/e) 1.06, 90% interval 0.99 to 1.13. Synonymous variants: 234 observed, 215.68 expected, observed/expected ratio (o/e) 1.08, 90% interval 0.97 to 1.21.
Gene-disease validity (ClinGen):
ClinGen rates the evidence that CYP7B1 causes each of these diseases.
CYP7B1-related disorder of oxysterol accumulation (autosomal recessive): Definitive. Any disorder of oxysterol accumulation caused by biallelic loss of function variants in the CYP7B1 gene.
Homologues: Orthologues: chimpanzee CYP7B1 (99% identical), macaque CYP7B1 (97% identical), dog CYP7B1 (73% identical), pig CYP7B1 (72% identical), guinea pig CYP7B1 (69% identical), rabbit CYP7B1 (66% identical), mouse Cyp7b1 (65% identical), rat Cyp7b1 (61% identical), tropical clawed frog cyp7b1 (49% identical), zebrafish cyp7b1 (41% identical). Paralogues in human: CYP7A1 (39% identical), CYP39A1 (25% identical).
Diseases named in the same sentence as CYP7B1 in open-access papers:
CYP7B1 is named in the same sentence as 89 diseases in open-access papers, as found by Europe PMC text mining. Sharing a sentence is not in itself a finding about the gene and the disease. The quoted sentences say what the papers report.
breast carcinoma (13 papers, 2015 to 2024). "We observed no significant heterogeneity in associations between circulating 27HC and breast cancer risk by CYP27A1 or CYP7B1 tumor expression though a statistically significant positive association between perimenopausal circulating 27HC and CYP7B1-negative breast cancer risk was observed." (PMID 32075687, 2020). "CYP7B1 has been shown to be associated with survival in both breast cancer and prostate cancer." (PMID 27341022, 2016). "Another important cohort study reported the negative correlation between circulatory 27-HC levels and CYP27A1, ER, LXRs, and CYP7B1 expression levels in breast cancer." (PMID 38550382, 2024). "Conversely, in ER + breast cancer cells, 27-HA promotes proliferation via hypermethylation of CYP7B1 and induction of CCL2, CCL3, and CCL4 chemokine levels." (PMID 38550382, 2024). "Immunohistochemical analysis with breast cancer patient tissues indicated a positive correlation between G9a expression and CYP7B1, a key enzyme of 27‐HC catabolism." (PMID 37614064, 2023). "The hypermethylation of CYP7B1 is also identified to play vital roles in accumulation of 27-hydroxycholesterol in breast cancer." (PMID 35190739, 2022). "The intra-tumor concentration of 27HC is around six-fold higher than those of normal breast tissues, and CYP7B1 gene expression is diminished in the majority of breast cancers, leading to an increase in the abundance of 27HC in breast cancer tumors." (PMID 32650428, 2020). "We observed no statistically significant heterogeneity in associations between circulating 27HC and breast cancer risk by tumor expression of CYP27A1, CYP7B1, LXR-β, or ERβ." (PMID 32075687, 2020). "In contrast, decreased expression of CYP7B1 triggers accumulation of 27-HC, and CYP7B1 was downregulated in breast cancer compared with normal breast tissue." (PMID 31311983, 2019). "This is the first study to analyse the expression of CYP7B1 in colorectal cancer, with previous research focusing on expression levels in prostate and breast cancer due to the role of CYP7B1 in sex hormone metabolism." (PMID 27341022, 2016). "In addition, elevated G9a expression was correlated with the increased expression of CYP7B1, the 27‐HC catabolising enzyme, in the tissues of patients with breast cancer in the premenopausal age group." (PMID 37614064, 2023). "We observed limited associations between breast cancer case characteristics and the investigated tumor markers, and no significant heterogeneity in associations between circulating 27HC and breast cancer risk by breast tumor CYP27A1, CYP7B1, or ERβ expression, and limited heterogeneity by LXR-β." (PMID 32075687, 2020). "Similar prognostic potential of CYP27A1 and CYP7B1 in breast cancer has been reported." (PMID 27341022, 2016). "High expression of the enzyme that catalyzes the conversion of cholesterol to 27HC, CYP27A1, is associated with higher tumor grade in breast cancers, and high expression of CYP7B1, the enzyme downstream of CYP27A1 is associated with better outcome in ER+ breast cancer patients." (PMID 26183823, 2015). "Cholesterol 27-hydroxylase (CYP27A1) and oxysterol 7-alpha-hydroxylase (CYP7B1) regulate 27HC concentrations, while differential expression of the liver X receptor (LXR) and estrogen receptor beta (ERβ) may impact the association between 27HC and breast cancer risk." (PMID 32075687, 2020). "Correlates of tumor protein expression of CYP27A1 and CYP7B1 with cancer characteristics, reproductive and lifestyle factors are not well established in cancer, including breast cancer." (PMID 32075687, 2020). "The CYP4Z1 30UTR could limit migration and EMT of breast cancer cells acting as a ceRNA for E-cadherin, and MicroRNA-17 induces EMT persistent with the cancer stem cell phenotype by controlling CYP7B1 expression in colon cancer." (PMID 31662772, 2019). "Furthermore, the association between circulating 27HC and breast cancer risk may not vary by tumor expression of CYP27A1, CYP7B1, LXR-β, or ERβ." (PMID 32075687, 2020).
Insulin resistance (12 papers, 2016 to 2025). Increased resistance towards insulin, that is, diminished effectiveness of insulin in reducing blood glucose levels. "Of note, as described by others and us before, Cyp7b1 is tightly associated with insulin resistance and cold-exposed Cyp7b1−/− mice seem to be insulin-resistant." (PMID 35478959, 2022). "In fact, CYP7B1 loss has been proposed as an early alteration in the course of the disease and may be related to the progression from insulin resistance to type 2-like diabetes." (PMID 41465421, 2025). "CYP7B1 loss has been proposed as an early alteration in the course of insulin resistance and may be related to the progression of the syndrome from insulin resistance to type 2-like diabetes and other liver pathologies." (PMID 41465421, 2025). "Recent report shows that insulin resistance dysregulates CYP7B1, and substantially increases the CA levels in liver tissue in mouse models of NAFLD." (PMID 37961761, 2024). "The authors provided strong evidence that the insulin resistance-mediated dysregulation of CYP7B1 establishes a cellular mechanism for the accumulation of “toxic” intracellular cholesterol metabolites." (PMID 38731981, 2024). "Lower Cyp7b1 mRNA expression was also observed in mouse models of insulin resistance and T2DM mice as well as in patients with obesity and T2DM47." (PMID 35440584, 2022). "In contrast, Cyp7a1 KO mice are also resistant to HFD-induced obesity, fatty liver, and insulin resistance due to induction of the alternative pathway Cyp27a1 and Cyp7b1 and the resultant increased production of the hydrophilic MCA." (PMID 35614477, 2022). "It was shown that the inability to upregulate CYP7B1 in the setting of insulin resistance results in the accumulation of toxic intracellular cholesterol metabolites that promote inflammation and hepatocyte injury." (PMID 34356103, 2021). "Further studies on these rats may help link CYP7B1 to precocious changes in the development of insulin resistance, particularly regarding hepatic secretion of TG-enriched VLDL and IGFBP2 levels via oxysterols." (PMID 41465421, 2025). "The reduction in Cyp7b1 expression was found in several genetic models of insulin resistance." (PMID 41465421, 2025). "Together, plasma parameters indicate that at thermoneutral (but not conventional) housing temperature, CYP7B1 deficiency enhances insulin resistance, dyslipidemia and liver damage in mice fed MAFLD-inducing diet." (PMID 34685636, 2021). "As LPL is activated by insulin also in BAT, and LPL activation is compromised by insulin resistance, reduced LPL levels in cold-housed Cyp7b1−/− mice might result from their insulin resistance." (PMID 35478959, 2022). "Collectively, we observed that mice lacking CYP7B1 exhibit signs of increased MAFLD-related fibrosis and accumulate liver lipids associated with inflammation and insulin resistance when housed at thermoneutral conditions." (PMID 34685636, 2021). "Cyp7b1 expression is negatively regulated by insulin resistance, which was not present in our study, and also by BA stimulation of FXR." (PMID 33374541, 2020).
Obesity (8 papers, 2012 to 2025). Accumulation of substantial excess body fat. "This might be explained by the reduced thermogenic activity and subsequent lower energy expenditure observed in Cyp7b1−/− mice, which ultimately results in the development of obesity." (PMID 35478959, 2022). "Thus, defective Cyp7b1 expression may be a component of obesity-related metabolic pathologies including hyperglycemia and hepatic steatosis." (PMID 22927828, 2012). "Our study showed that UDCA administration in mice enhanced CYP7B1 expression but reduced CYP8B1 expression, leading to an elevated non-12-OH/12-OH BA ratio and a decrease in diet-induced obesity." (PMID 33252713, 2021). "In this study, MOP supplementation increased Cyp7a1 and Cyp7b1 expression in the liver compared to the HFD group, suggesting that MOP may prevent obesity by regulating bile acid metabolism." (PMID 35548566, 2022).
Hepatic steatosis (7 papers, 2012 to 2023). Steatosis is a term used to denote lipid accumulation within hepatocytes. "Ambient temperature is an important determinant of both the alternative bile acid synthesis pathway controlled by oxysterol 7-α hydroxylase (CYP7B1) and the progression of metabolic-associated fatty liver disease (MAFLD)." (PMID 34685636, 2021). "Forced overexpression of Cyp7b1 improved hepatic steatosis but eventually suppressed bile acid excretion and caused cholestasis." (PMID 22927828, 2012). "In addition, Cyp7b1 expression was negatively associated with hepatic steatosis in an animal model." (PMID 26619823, 2015). "More recently, we have reported that dietary coffee preserved hepatic Cyp7b1 and Sult2b1 mRNA and protein expressions, thereby maintaining physiologic levels of 26HC/3βHCA in a WD-induced fatty liver mouse model." (PMID 37408268, 2023). "Modulating gut microbiota with an antibiotic cocktail can alleviate HFD-induced hepatic steatosis and inflammation in hamsters via upregulating cytochrome P450 family 7 subfamily B member 1 (CYP7B1) to increase hydrophilic BA synthesis." (PMID 34944709, 2021). "Cyp7b1-overexpressing mice exhibited improved hepatic steatosis as measured by total triglyceride levels and haemotoxylin Eosin (H&E) staining." (PMID 22927828, 2012). "Similarly, the overexpression of Cyp7b1 has been found to lower fasting glucose levels and improve hepatic steatosis in ob/ob mice." (PMID 37408268, 2023).
atherosclerosis (6 papers, 2013 to 2023). A disease characterized by the build-up of fatty material and calcium deposition in the arterial wall resulting in partial or complete occlusion of the arterial lumen. "Previous research has found that elevations in 27HC via the deletion of CYP7B1 can cause exaggerated atherosclerosis." (PMID 36647013, 2023). "CYP7B1 is a 27HC metabolizing enzyme and elevations in 27HC via Cyp7b1 deletion promote atherosclerosis in Apoe−/− mice." (PMID 36316327, 2022). "Deletion of Cyp7b1 leading to increased 27-HC levels or direct injection of 27-HC promoted atherosclerosis in mice due to multiple proinflammatory effects mediated through attenuating ERα receptor function on endothelial cells and macrophages." (PMID 32998240, 2020). "Elevations in 27HC via Cyp7b1 deletion promote atherosclerosis in Apoe−/− mice." (PMID 36316327, 2022). "Elevated 27-HC concentrations promoted atherosclerosis in APOE−/− Cyp7b1−/− mice." (PMID 32998240, 2020). "Additionally, an elevation of 27-hydroxycholesterol in cyp7b1 KO/apoE KO mice exacerbated atherosclerosis and subcutaneous injection with 27-hydroxycholesterol to apoE KO mice increased atherosclerosis." (PMID 31382484, 2019). "The Cyp7b1 may also be involved in the development of atherosclerosis, oxysterol metabolism, and sex hormone synthesis." (PMID 25393872, 2014). "It is likely that CLA mediated regulation of both PGC-1α and RORα may regulate Cyb7b1 since it has previously been shown that in RORα−/− mice, which develop severe atherosclerosis, there is suppression of Cyp7b1 expression suggesting RORα may be a positive regulator of Cyp7b1." (PMID 23964012, 2013).
cholestasis (5 papers, 2012 to 2025). Impairment of the bile flow caused by obstruction within the liver, or outside the liver in the bile duct system. "Previous works have shown that Cyp7b1−/− mice accumulated 25-HC in the liver, and that CYP7B1 loss-of-function in human leads to severe cholestasis/cirrhosis in early life." (PMID 41275524, 2025). "Congenital bile acid synthesis disorder type 3 (CBAS3) is an extremely rare subtype caused by deficiency of oxysterol 7α-hydroxylase encoded by the cytochrome P450 7B1 (CYP7B1) gene, manifesting obvious cholestasis in the neonatal period with progressive aggravation and liver enlargement." (PMID 35387662, 2022). "Her 15-year-old brother, with no history of infantile cholestasis but harboring the same mutations in CYP7B1, had gait abnormality from 13 years of age." (PMID 33849447, 2021). "The development of cholestasis in the Cyp7b1-overexpressing ob/ob liver was not caused by increased cholesterol biosynthesis and bile formation." (PMID 22927828, 2012). "However, caution has to be exercised concerning the role of Cyp7b1 in metabolic regulation, because constitutive overexpression of Cyp7b1 also led to the development of cholestasis." (PMID 22927828, 2012).
prostate carcinoma (5 papers, 2016 to 2024). A carcinoma that arises from epithelial cells of the prostate gland. "In this study, we aimed to analyze the association between CYP7B1 and prostate cancer, along with its association with proteins involved in cancer and metabolic processes." (PMID 38731981, 2024). "We aimed to analyze the association between CYP7B1 and prostate cancer, along with its association with proteins involved in cancer and metabolic processes." (PMID 38731981, 2024). "It has been observed that an increased expression of CYP7B1 is associated with more aggressive forms of prostate cancer, indicating a potential link between this enzyme and the progression of the disease." (PMID 38731981, 2024). "The association between CYP7B1 and prostate cancer aggressiveness is multifaceted and involves the modulation of androgen metabolism, intratumoral androgen levels, and the interaction with steroid hormone pathways." (PMID 38731981, 2024). "This association was also investigated in prostate cancer showing correlation between CYP7B1 expression and androgen signaling activity." (PMID 32075687, 2020). "In our immunohistochemical analysis of malignant and benign prostate tissue, we revealed an increased expression of CYP7B1 in men with prostate cancer and an association between an increased risk of biochemical recurrence in a subgroup analysis of men without diabetes." (PMID 38731981, 2024). "The expression of CYP7B1 has been shown to be upregulated in prostate cancer and it is also been demonstrated that a single polymorphism in the promoter of this gene has an effect on its expression." (PMID 35870994, 2022). "Of the 139 patients with elevated CYP7B1 expression, 92.8% had prostate cancer." (PMID 38731981, 2024). "Among the 139 patients with elevated CYP7B1 expression, 92.8% were diagnosed with prostate cancer." (PMID 38731981, 2024). "Additionally, targeting CYP7B1 or its downstream pathways could represent a novel therapeutic strategy for managing aggressive forms of prostate cancer." (PMID 38731981, 2024). "Consequently, the combination of low levels of 3βAdiol (a weaker androgen metabolite) and increased CYP7B1 expression, along with a decreased expression of ERβ, is unfavorable and likely to play a significant role in the initial stages of prostate cancer development." (PMID 38731981, 2024). "Interestingly, the CYP27A1 expression level is inversely correlated to prostate cancer development and progression, while the CYP7B1 enzyme level is significantly upregulated during prostate cancer prognosis, suggesting that 27HC might be actually beneficial against prostate cancer." (PMID 32650428, 2020). "In the present study, we aimed to explore the relationships between the expression of certain genes (CYP7B1, SRSF-1, FAS, PSMA, ACC-1, CPT1a, and SREBP) and oncological factors in prostate cancer patients with and without diabetes." (PMID 38731981, 2024).